ZEB1 (zinc finger E-box binding homeobox 1)
Diseases named in the same sentence as ZEB1 in open-access papers (continued):
Sharing a sentence is not in itself a finding about the gene and the disease.
renal fibrosis (continued). "Zeb1 knockdown abrogates the profibrogenic effect of MRTF-A in renal fibroblasts in vitro, whereas mice with myofibroblast-specific depletion of Zeb1 phenocopied the MRTF-AMFKO mice in two different animal models, pointing to Zeb1 as a downstream mediator of MRTF-A in FMyT and renal fibrosis." (PMID 37121967, 2023). "However, Zeb1 depletion improved renal function, as determined by plasma BUN and creatinine levels, and mitigated renal fibrosis, as determined by qPCR measurements of profibrogenic gene expression and PSR/Masson’s staining." (PMID 37121967, 2023). "All of these results indicate that the protective effects of BPP on the renal fibrosis and EMT in UUO mice or TGF‐β1‐induced HK‐2 cells are at least partially achieved by inhibiting the expression levels of transcription factors, including Snail, Twist and ZEB1." (PMID 33507617, 2021). "Although the function of Wnt11 and Wnt6 in liver fibrosis was unknown, Wnt11 was shown to enhance the expression of mesenchymal markers, such as Zeb1, Snail1, Pai1 and α-SMA, in response to the TGF-β signaling in renal fibrosis, and Wnt6 was reported to be downregulated during renal fibrogenesis." (PMID 27322257, 2016). "In a third model, of renal fibrosis induced by diabetic nephropathy,created by injecting mice with STZ followed by HFD feeding, Zeb1 depletion did not alter body weight or plasma glucose levels." (PMID 37121967, 2023). "Indeed, manipulation of Zeb1 in myofibroblasts attenuated renal fibrosis without altering renal function in two acute models (UUO and IRI), whereas the same procedure both improved renal function and mitigated renal fibrosis in a more chronic model (diabetic nephropathy)." (PMID 37121967, 2023).
metastatic tumors (17 papers, 2012 to 2025). "The ROC analyses, even performed on a limited number of samples, identified the cut-off levels of CDH1, CDH5, and ZEB1 genes useful for the possible diagnostic identification of primary or metastatic tumors." (PMID 40332096, 2025). "Another interesting finding from our transcriptomic study is that ZEB1 is upregulated in de novo metastatic tumors." (PMID 37686617, 2023). "Conversely we observed genes associated with aggressive metastatic disease and EMT (VIM, SPARC, ZEB1, SNAI2, CTSB) upregulated in lung populations compared to lymph nodes." (PMID 34579762, 2021). "Vimentin, along with Zeb1, are widely regarded as markers of EMT and have been implicated in the development of metastatic disease in many cancers, including prostate." (PMID 32986721, 2020). "IHC staining of metastatic tumors with E-cad and ZEB1 revealed that MET had occurred in tumor cells that express OVOL1 or ZEB1-shRNA, as indicated by positive E-cad and lowered ZEB1 expression in contrast to the mesenchymal control cells." (PMID 24124593, 2013). "Furthermore, the expression of Snail, Twist1, and ZEB1 was higher in metastatic tumors than in non‐metastatic tumors." (PMID 40259641, 2025). "Thus, our results add further details regarding the role of ZEB1 in cancer diagnostics, suggesting its possible function in discriminating patients suffering from metastatic tumors from primary tumors." (PMID 40332096, 2025). "Zeb1 and Twist are more commonly expressed in metastatic tumors compared to the primary tumors and Twist may function upstream of Snail and Zeb1." (PMID 22701711, 2012). "Moreover, Snail, Twist1, and ZEB1 staining show increased intensity in metastatic tumors, which may contribute to lung metastasis in mice bearing subcutaneous tumors." (PMID 40259641, 2025). "The shorter OS and/or PFS associated with the RNA expression of ZEB1 and SNAI1 by CTCs may indicate a more aggressive and potentially docetaxel resistant phenotype being present in the primary or metastatic tumour sites, which may promote disease progression in mHSPC patients." (PMID 36727071, 2022). "Members of the Snail family of transcriptional repressors (e.g., SNAIL and SLUG) and other repressors of E-cadherin gene expression, such as ZEB1, ZEB2, and TWIST1, have been detected at EMT sites at the leading edge of metastatic tumors." (PMID 40490818, 2025). "We found that the expression of TWIST1, SNAI1, ZEB1, hFN1, and MMP2 increased from healthy epithelial cells to primary and metastatic tumor cells, reaching the highest expression in mesenchymal cell models." (PMID 40332096, 2025). "Note that expression of SNAIL2, ZEB1, ZEB2, TWIST2 was significantly lower in the distant metastatic tumors (Met_distant, n = 628) than other subgroups." (PMID 35272617, 2022). "Our data indicated that gene expression of ZEB1, a major transcription factor in EMT, can predict TRPC1 mRNA expression, both in primary and metastatic tumors." (PMID 34936030, 2021). "Knockdown of ZEB1 in MHCC-97H cells significantly decreased the weight and size of primary tumor and the number of metastatic tumors on the surface of liver." (PMID 33897890, 2021). "Meanwhile, the level of E-cadherin protein decreased, while the levels of N-cadherin, Snail, Slug, ZEB1, and ZEB2 proteins increased, in metastatic tumors with FOXM1 knockdown." (PMID 32513952, 2020). "ZEB1 and YAP represent well-known vulnerabilities that could be exploited for the treatment of metastatic tumors." (PMID 35477522, 2022).
pancreatic ductal adenocarcinoma (17 papers, 2015 to 2026). An infiltrating adenocarcinoma that arises from the epithelial cells of the pancreas. "To investigate the broader relevance of the miR-200–Zeb1 axis in epithelial cancers, we crossed the mutated Zeb1 allele into the pancreatic ductal adenocarcinoma (PDAC) “KPC” model." (PMID 30405106, 2018). "The importance of ZEB1 was highlighted by Bronsert and colleagues, who showed that stromal ZEB1 was an independent marker of prognosis in patients who have undergone resection for pancreatic ductal adenocarcinoma." (PMID 35595718, 2022). "CD44 knockdown using CD44 shRNA in pancreatic ductal adenocarcinoma cells not only efficiently reduced the expression of Zeb1 and Snail1 but also significantly impaired cell proliferation and invasion." (PMID 34944493, 2021). "In pancreatic ductal adenocarcinoma, the increased ZEB1 protein expression is due to its shorted 3’UTR." (PMID 31039132, 2019). "Similar observations were reported for the ZEB1 protein in a study of 117 pancreatic ductal adenocarcinomas." (PMID 28544627, 2017). "(2014) identified stromal ZEB1 expression as an independent predictor of survival after resection of pancreatic ductal adenocarcinoma." (PMID 28544627, 2017). "To investigate the role of metabolic plasticity in metastasis, we employed murine pancreatic ductal adenocarcinoma (PDAC) cell lines with distinct EMT states, ZEB1 expression and lung colonization capacities." (PMID 42155637, 2026). "In a liver metastasis model of PDAC (pancreatic ductal adenocarcinoma), treatment with a NTN1-neutralizing antibody or tumoral knockdown of Neo1 reduced ZEB1 and SOX9 and decreased tumor progression." (PMID 40777309, 2025). "Neutrophils secrete NE, which cleaves E-cadherin on tumor cell surfaces while inducing nuclear translocation of β-catenin and Zeb1, promoting tumor cell EMT in pancreatic ductal adenocarcinoma." (PMID 40564191, 2025). "In pancreatic ductal adenocarcinoma (PDAC), treatment with genotoxic agents induces shortening of ZEB1 3′UTR which increases ZEB1 protein production through escaping from repression by miRNAs such as miR-200." (PMID 36114510, 2022). "In pancreatic intraepithelial neoplasia and pancreatic ductal adenocarcinoma, CD44 is central in promoting the upregulation of EMT biomarkers expression, Snail1 and Zeb1, as well as stimulating migration and invasion." (PMID 34944493, 2021). "TrkB is overexpressed in several human cancers, ranging from neuroblastomas to pancreatic ductal adenocarcinomas, and its overexpression suppresses anoikis as an EMT inducer by regulation of Zeb1." (PMID 26515594, 2015). "Such a negative ZEB1 translation regulator has been described for pancreatic ductal adenocarcinoma cells." (PMID 41226394, 2025). "Supporting the transcriptional data, we detected ZEB1 positive (+) CD68+ macrophages by immunofluorescence (IF) stainings of human CRC and mouse lung metastases formed upon tail vein injection (tvi) of pancreatic ductal adenocarcinoma (PDAC) cells." (PMID 40595293, 2025). "Notably, in human pancreatic ductal adenocarcinoma cells (PDAC), the TF ZEB1 binds clustered elements predominantly nearby chromosomal telomeres." (PMID 40131776, 2025).
esophageal cancer (16 papers, 2016 to 2025). A primary or metastatic malignant neoplasm involving the esophagus. "Next, in order to unveil the underlying molecular mechanism of TRIM9's impact on esophageal cancer, we further explore the expression level association between ZEB1 and TRIM9." (PMID 37124931, 2023). "To further explore the underlying mechanisms of 5-FU resistance in these three esophageal cancer cell lines, we examined the changes in EMT-related proteins, such as E-cadherin, and EMT transcription factors, including Slug and ZEB1." (PMID 40427135, 2025). "TGF-β overexpression then forms a positive feedback loop with ZEB1 to elevate esophageal cancer EMT induction and progression." (PMID 38733529, 2024). "And TRIM9 inhibited esophageal cancer tumor expansion, invasion, and metastasis through interaction with ZEB1, which accelerated its protein degradation through the UPP pathway." (PMID 37124931, 2023). "VIP and ZEB1 expression were both lower in stomach, colon, and esophageal cancer tissue compared to healthy tissue (p < 0.0001)." (PMID 37444395, 2023). "And TRIM9/ZEB1 knockout in vitro or in vivo models also will be of value in validating the role of the TRIM9-ZEB1 axis in esophageal cancer pathogenesis and progression." (PMID 37124931, 2023). "Results from the TRIM9 mRNA and protein quantification study of esophageal cancer samples suggested that ZEB1 protein levels were significantly correlated with TRIM9 (p < 0.001), but for their mRNA expression levels, no notable correlation was detected." (PMID 37124931, 2023). "SNHG16 induces cell proliferation, migration and EMT process of esophagus cancer through targeting miR-140-5p/ZEB1 axis." (PMID 32432654, 2020). "The biogenesis of circ-DOCK5 is inhibited in esophageal cancer by ZEB1." (PMID 38733529, 2024). "The immunohistochemistry results showed that the expression of FOXP2 in cytoplasm increased with the pathological grade, which was similar to the decreasing cytoplasmic expression of transcription factor ZEB1 in tumor tissues of patients with low grade esophageal cancer." (PMID 30728054, 2019). "Finally, in order to further investigate the role of TRIM9-ZEB1 interaction in the malignant phenotype of esophageal cancer cells, ZEB1-specific overexpression vectors were utilized, and their regulatory function on ZEB1 mRNA and protein expression was validated." (PMID 37124931, 2023). "Also, given that HNRNPC was reported to interact with ZEB1 to stabilize its mRNAs in esophageal cancer, we therefore hypothesized that HNRNPC could possibly directly interact with ZEB1 mRNAs to prolong their stability in oral cancer cells." (PMID 35963855, 2022). "However, whether TRIM9 could regulate esophageal cancer by affecting ZEB1 remains unclear." (PMID 37124931, 2023). "Subsequent investigations suggested that TRIM9-ZEB1 interaction accelerated ZEB1 protein degradation through the modulation of the UPP pathway, which confirmed the protective role of TRIM9 in esophageal cancer progression and metastasis." (PMID 37124931, 2023). "In esophageal cancer, RAB11FIP1 regulates EMT by directly inhibiting the key transcription factor ZEB1 of EMT." (PMID 34764984, 2021). "Overexpression of PD-L1 enhances the levels of mesenchymal genes (ZEB1, N-cadherin, and Vimentin), and contributes to the EMT phenotypes of esophageal cancer cells." (PMID 33363153, 2020). "Functional experiments including transwell assay, cell viability assay, and ubiquitination blocking experiments were performed to evaluate the role of the TRIM9/ZEB1 (zinc finger E-box binding homeobox 1) axis and UPP pathway in esophageal cancer progression and exacerbation." (PMID 37124931, 2023).
lymph node metastasis (16 papers, 2014 to 2025). "Therefore, ZEB1 can be used to predict the risk of lymph node metastasis by its preoperative characteristics." (PMID 36701720, 2023). "Zinc finger E-box-binding homeobox 1 positively correlated with lymph node metastasis (r = 0.68), stage (r = 0.72), and grade (r = 0.56), whereas E-cadherin showed negative correlations (r = −0.60, −0.59, and −0.52, respectively)." (PMID 40787244, 2025). "Clinical analysis showed that ZEB1 overexpression is closely related to malignant progression, lymph node metastasis, and the poor prognosis of GC patients." (PMID 38965605, 2024). "Expression of EBNA1 has also been found to be associated with lymph node metastasis and able to upregulate the EMT mediators zinc finger E-box binding homeobox 1 (ZEB1) and ZEB2." (PMID 29617291, 2018). "ERβ1 expression was negatively correlated with ZEB1 expression and lymph node metastasis, and positively correlated with the expression of AR and E-cadherin." (PMID 28583190, 2017). "ZEB1 expression greater than 4.92 demonstrated a sensitivity and specificity of 57.8% and 74.1%, respectively, for lymph node metastasis (ROC AUC = 0.657; 95% CI, 0.541–0.774)." (PMID 25544793, 2014). "Immunohistochemical analysis indicated a substantial association of ZNF248 expression with the lymph node metastasis, and with the liver metastasis (P =0.01, P =0.01), and a positive correlation between ZNF248 and ZEB1 expression (P =0.021) was also identified." (PMID 39247604, 2024). "ZEB1 expression could help physicians to better predict the lymph node metastasis in the patients prior to hysterectomy." (PMID 33066317, 2020). "Based on combination of preoperative characteristics and ZEB1 expression, lymph node metastases could be identified with a sensitivity of 62.1% at specificity of 96.2% prior to hysterectomy." (PMID 25544793, 2014). "Based on the combination of preoperative characteristics and ZEB1 expression, lymph node metastases could be identified with a sensitivity of 62.1% at specificity of 96.2%." (PMID 25544793, 2014). "Lymph node metastases could be identified with a sensitivity of 57.8% at specificity of 74.1% by ZEB1 expression in endometrial biopsy." (PMID 25544793, 2014). "Furthermore, lymph node metastases could be identified with a sensitivity of 62.1% at specificity of 96.2% by combination of preoperative characteristics and ZEB1 expression." (PMID 25544793, 2014). "The expression levels of E-cadherin and zinc finger E-box-binding homeobox 1 were analyzed in 50 Iraqi patients diagnosed with PTC without lymph node metastases, evaluated between January 2015 and December 2021." (PMID 40787244, 2025). "Between ZEB1 expression in patients with lymph node metastasis (5.31 ± 3.15) and without lymph node metastasis (3.37 ± 3.02), a significant difference has been found (P < 0.001)." (PMID 25544793, 2014). "We also found that ZEB1 expressions in patients with lymph node metastasis were significantly higher than those in patients without lymph node metastasis." (PMID 25544793, 2014). "ZEB1 expression was lower in BC patients with lymph node metastasis than in those without." (PMID 35905576, 2022). "In addition, ZEB1 was lower in BC tissues with lymph node metastasis than in those without metastasis." (PMID 35905576, 2022). "Furthermore, the expression of ZEB1 was corrected with histological grade and lymph node metastasis (P < 0.05), which was not related to patients age." (PMID 31007650, 2019).
acute myeloid leukemia (15 papers, 2017 to 2026). Acute myeloid leukemia (AML) is a group of neoplasms arising from precursor cells committed to the myeloid cell-line differentiation. "Within the myeloid lineage, however, there is emerging evidence that ZEB2 and ZEB1 may both potentially contribute to the development and/or maintenance of acute myeloid leukemia (AML)." (PMID 34550965, 2021). "Finally, we find that Zeb1-mediated regulation of these stem cell fates is required to suppress malignancy in the context of acute myeloid leukemia (AML)." (PMID 33108352, 2021). "In acute myeloid leukemia (AML) cells, ZEB1 directly promotes the development of Th17 cells, and conversely, the expansion of Th17 cells creates a pro-invasive phenotype, favoring the transcription of genes Interleukin-23 (IL-23)." (PMID 40016707, 2025). "ZEB1, a prominent transcription factor of the EMT, plays a significant part in stemness and the progression of acute myeloid leukemia (AML)." (PMID 39941895, 2025). "Overexpression of MALAT1 was investigated in acute myeloid leukemia (AML) patients and AML cell lines, and was found to promote cancer progression via mA RNA modification of ZEB1 gene." (PMID 37266436, 2023). "Finally, inactivation of Zeb2 alone or Zeb1/2 together was found to enhance survival in secondary MLL-AF9 acute myeloid leukemia (AML) models attesting to the oncogenic role of ZEB1/2 in AML." (PMID 34550965, 2021). "In the case of acute myeloid leukemia, H4R3me2a participates in epithelial–mesenchymal transition (EMT) by regulating zinc finger E-box binding homeobox 1 (ZEB1) promoter, while its demethylation under the influence of specific factors is implicated in leukemic transformation." (PMID 38473745, 2024). "In acute myeloid leukemia (AML), poor patient prognosis correlated with the expression of EMT markers, and experimental downregulation of ZEB1 in AML cells inhibited the invasive capacity of this aggressive cancer." (PMID 39736693, 2024). "Overall, the ZEB1 and ZEB2 transcription factors play important roles in the progression and aggressiveness of acute myeloid leukemia (AML) by influencing the epithelial–mesenchymal transition, stem cell characteristics, and therapy resistance." (PMID 39200378, 2024).